EDN1 (endothelin 1)
Diseases named in the same sentence as EDN1 in open-access papers (continued):
Sharing a sentence is not in itself a finding about the gene and the disease.
Hypertension (continued). "In addition, T cells and macrophages contain all the machinery needed for the production of vasoactive molecules such as angiotensin II, endothelin-1, or prostaglandins, which are known mediators of hypertension and hypertension-induced end-organ damage." (PMID 33494430, 2021). "Elevated IgG aβ2GPI directly relates to endothelin-1 and to isoprostane, two powerful vasoactive agents, and inversely relates to nitric oxide metabolites, leading to increased vasomotor tone and arterial hypertension." (PMID 34300346, 2021). "Moreover, the relationship between hypertension and excessive expression of endothelin-1 (ET-1) in the endothelium has been shed lighted by increasing studies." (PMID 34072901, 2021). "The PPARγ agonists rosiglitazone and pioglitazone exert beneficial effects in several aspects of PH including: suppression of pro-inflammatory cytokines such as TGF b and metalloprotease, suppression of angiotensin-II induced hypertension, and reduction of endothelin-1 levels." (PMID 33535425, 2021). "The sex differences in vascular tone and hypertension may be also related to differences in the production of or sensitivity to endothelium-derived contracting factors, such as endothelin-1 (ET-1)." (PMID 34501285, 2021). "VEGF signaling plays a key role in angiogenesis; blocking this pathway not only has antitumor effects but also leads to accelerated hypertension possibly via decreased nitric oxide bioavailability, increased endothelin-1 production, or microvascular rarefaction." (PMID 34630076, 2021). "A hyperglycaemic state prompts the kidneys to release vascular endothelial growth factor (VEGF) and NO to expand afferent glomerular arterioles and release angiotensin II (AngII) and endothelin-1 (ET-1) to contract efferent arterioles, which leads to high blood pressure and the occurrence of DN." (PMID 34364389, 2021). "In addition, numerous studies have revealed that the excessive expression of endothelin-1 (ET-1) in the endothelium makes a positive contribution to hypertension and atherosclerosis, which are the major precursors of cardiovascular diseases." (PMID 32121212, 2020). "And by analyzing endothelin-1 and lipid peroxides in the serum of pregnant women with hypertension, a decrease in the level of abnormal oxidation reaction substances in pregnant women with hypertension supplementing vitamin E was shown." (PMID 33014274, 2020). "Endothelin-1 (ET-1), a potent vasoconstrictor peptide with mitogenic and atherogenic effects on the smooth muscular cells, plays an important role in BP control in cortisol-induced hypertension." (PMID 31164868, 2019). "Our results revealed that EDN1 rs5370 polymorphism was associated with LAS development both before and after adjustment for atherosclerosis risk factors (sex, age, body mass index, arterial hypertension, type 2 diabetes mellitus, and smoking)." (PMID 29849817, 2018). "We study whether hypertension is due to endothelin-1 or nitric oxide (NO) production alterations in STS and LTS rats." (PMID 29882756, 2018). "Our previous work indicated that forest bathing lowered the circulating endothelin-1 (ET-1) level in normal young subjects or old patients with hypertension, which is known as one of the most potent vasoconstrictors and is always recognized as a stimulator on cardiovascular diseases." (PMID 28362327, 2017). "The effect of hypertension on CKD progression among different genotypes of the EDN1 polymorphisms is almost similar and no confounding effect was observed." (PMID 28197493, 2016). "The mechanisms by which hyperleptinemia contributes to hypertension include the following: activation of the sympathetic nervous system innervating the kidneys, increase in circulating endothelin-1 (ET-1), increase in oxidative stress, decrease in nitric oxide and increase in sodium retention." (PMID 25793389, 2015).
Hypertension (continued). "Likewise, inhibition of the VEGF receptors by small molecule tyrosine kinase inhibitors increases blood pressure, at least partially mediated by increased endothelin-1 expression – a known final effector of hypertension in preeclampsia patients." (PMID 25249978, 2014). "Accumulating evidence from clinical and experimental studies indicates that angiotensin II (Ang II)/angiotensin II type 1 receptor (AT1R) and endothelin (ET)-1/ endothelin-1 type A receptor (ETAR) have important roles in hypertension and pathological remodeling of the heart." (PMID 24685050, 2014). "Endothelin-1 (ET-1), a potent vasoconstrictor and pressor agent involved in the regulation of blood pressure, has been shown to play a crucial role in the development of hypertension in experimental animal models of placental hypoxia/ischemia." (PMID 24904422, 2014). "Further research need to focus on more inflammatory biomarkers such as intercellular adhesion molecule-1 (ICAM-1), endothelin-1, and others as well as their pathways to understand the possible molecular mechanisms involved in the inducing of hypertension by heated palm oil." (PMID 22778962, 2012). "Other investigators suggest that endothelin-1 may play an important role in the development of hypertension among psoriasis patients." (PMID 21479272, 2011). "Hypertension is largely due to inappropriate humoral control precipitated by increased oxidative stress, increased production of endothelin-1 (ET-1), decreased nitric oxide (NO) production and/or bioavailability, and/or over-stimulation of the renin-angiotensin system (RAS)." (PMID 27713250, 2010). "Additionally, obesity-related metaflammation disrupts endothelial balance by decreasing nitric oxide (NO) availability and increasing levels of asymmetric dimethylarginine (ADMA) and endothelin-1 (ET-1), which promote vasoconstriction, vascular remodeling, and hypertension." (PMID 40977717, 2025). "Endothelin-1, nitric oxide, and serotonin are known modulators of vascular reactivity, and their imbalance has been implicated in the development and persistence of high blood pressure, even in the absence of structural heart disease." (PMID 41010423, 2025). "Finally, the genetic risk locus on chromosome 6p24, which contains PHACTR1 and EDN1 genes, is associated with multiple vascular diseases, including CAD, migraine headache, coronary calcification, hypertension, fibromuscular dysplasia, microvascular angina, and arterial dissection." (PMID 38627847, 2024). "Although the mechanism of TCEs in treating hypertension is not clear, the increase in endogenous nitric oxide (NO) production and the decrease in endothelin-1 (ET-1) in plasma after TCEs therapy may be one of the main biological mechanisms of TCEs in treating essential hypertension." (PMID 38481952, 2024). "Furthermore, it may have implications in models of hypertension that affect renal function, such as endothelin 1-induced hypertension." (PMID 37075761, 2023). "In addition, quercetin also has a hypotensive effect in pregnancy induced hypertension, which may be related to the regulation of endothelin 1 (ET-1) and endothelin 1A receptor (ETAR)." (PMID 38054093, 2023). "However, this study can prove that hypertension is significantly related to the + 138 Ins/del A polymorphism of EDN1 gene, while the effect of the + 5665 G/T polymorphism is not significant on hypertension in Burmese people, Myanmar." (PMID 35841119, 2022). "Endothelin-1 may contribute to VEGF receptor inhibitor-related hypertension." (PMID 35566115, 2022). "The mechanisms involved in arsenic-induced hypertension are endothelium dysfunction and calcium sensitization disrupting the antioxidant defense mechanism and stimulating beta adrenoreceptors, thus hyper-activating the sympathetic system (enhancing the expression of endothelin-1)." (PMID 36362997, 2022). "Therefore, EDN1 is considered a potential therapeutic drug target in hypertension." (PMID 35205232, 2022).
Hypertension (continued). "Similarly, experimental study indicated that O3 treatment may decrease blood pressure and prevent hypertension progression with the mechanisms of reducing the levels of serum endothelin-1 and ET receptor A mRNA expression." (PMID 36249254, 2022). "In addition to diabetes, increased O-GlcNAc levels have been reported in different experimental models of hypertension, cardiac hypertrophy, cardiac dysfunction, as well as in response to agonists such as angiotensin II (Ang II) and endothelin-1 (ET-1)." (PMID 35371030, 2022). "The earlier on-set of hypertension among men in this study may be explained by the lower oestrogen levels, but increased activities of the sympathetic nervous system and endothelin-1 leading to increased vasoconstriction and high blood pressure levels compared to premenopausal women." (PMID 34383770, 2021). "Thus, our study highlighted the obvious relationship between psoriasis and hypertension in the pediatric age group which probably results from an imbalance between vasoconstriction factors like (endothelin-1 and angiotensin-2) and vasodilation factors (nitric oxide and prostacyclin)." (PMID 34729275, 2021). "Therefore, the effect of Qigong on the levels of nitric oxide and endothelin-1 may be a potential mechanism to reduce hypertension." (PMID 34659434, 2021). "In addition, the plasma endothelin-1 level in patients with essential hypertension was not different in individuals with the Asn allele and Lys/Lys genotype." (PMID 29849817, 2018). "In rats, blockade of TNF-α signaling by etanercept partially attenuates the hypertension associated with placental ischemia, and infusion of TNF-α to levels seen in rodents with placental ischemia leads to a hypertensive phenotype associated with increased vascular production of endothelin-1." (PMID 25249978, 2014). "In hypertension, the delicate balance between vasodilators and vasoconstrictors produced by the endothelium is disrupted, with disturbance in the NO pathway leading to predominance of vasoconstrictors such as endothelin 1 (ET-1), which contribute to high blood pressure." (PMID 24289091, 2013). "Additionally, anti-angiogenic drugs used in human patients have been shown to induce increased concentrations of endothelin-1, and this may contribute to the observed hypertension." (PMID 24079884, 2013). "There are proposed some hypothetical mechanisms leading to hypertension related to sunitinib, e.g. presence of less-perfused microvessels and/or diminished number of microvessels, decreasing nitric oxide production and activation of the endothelin-1 pathway leading to vasoconstriction." (PMID 22439647, 2012). "A reliable marker of vasoconstriction and vascular tone is endothelin-1 (ET1), directly secreted by the endothelial cells in response to renin angiotensin system activation, hyperglycemia, hypertension and systemic inflammation." (PMID 36671558, 2023). "Recent studies have shown that hypertension activates RAAS, increases Ang II level and endothelin-1 (ET-1) expression, stimulates vascular endothelial injury, increases ROS production and promotes oxidative stress." (PMID 37353787, 2023). "TNF-α alone induces symptoms of PE in animal models including hypertension, FGR, oxidative stress, Endothelin-1 and AT1-AA in pregnancy." (PMID 36909242, 2023). "Endothelial cell activation of endothelin-1 (ET-1) by Ang II, a vasoconstrictor peptide, is another route for BPA-induced hypertension." (PMID 36422227, 2022). "Several pathways have been showed to activate NAD(P)H oxidase in Ang II-dependent or DOCA-salt–induced hypertension, including Ang II/AT1aR activation, direct PRR activation, and enhanced endothelin-1 signaling." (PMID 36139008, 2022). "ADM, EDN1, ANGPTL4, NFIL3, MSR1, CEBPD, and USP8, based on their FDR values (<0.05, p-values (≤0.05)), were the top DEGs for hypertension." (PMID 35205232, 2022).
Hypertension (continued). "Another mechanism involves the increased production of endothelin-1, along with hyperactivation of the RAS increasing oxidative stress, which has been known to promote SLE hypertension." (PMID 35770194, 2022). "For decades, the pathophysiology of arterial hypertension has primarily been attributed to vasoconstriction hormones, including RAAS, prostaglandins, and endothelin 1 (ET1)." (PMID 31052201, 2019). "Circadian profile of endothelin-1, epoxyeicosatrienoic acids (EETs) and calcitonin generelated peptide (CGRP) in plasma of rats with 1K-1C model of arterial hypertension (1K-1C AH)." (PMID 31673274, 2019). "Besides, this plant significantly prevented hypertension and vascular dysfunction in hypertensive rats by inhibiting the secretion of ICAM-1 and the levels of serum endothelin-1 (ET-1)." (PMID 37396948, 2023). "Given the critical roles of Ang II, endothelin-1 (ET-1), and H2O2 in hypertension and vascular diseases, we aimed to explore whether they regulate the expression of Sp1 and Sp3 in endothelial cells." (PMID 37735515, 2023). "Other hypotheses suggest that activin A involvement in preeclampsia pathogenesis rely on endothelin-1, ICAM-1 and VCAM-1 overexpression, favouring hypertension and oedema." (PMID 37595293, 2023). "Endothelin-1 (ET-1), the most potent endogenous vasoconstrictor, generated by enzymatic cleavage catalyzed by an endothelin-converting enzyme (ECE), plays a significant role in the regulation of hypertension." (PMID 35645613, 2022). "On the other hand, rhEPO has been observed to foster the production of two molecules, endothelin 1 (ET-1) and plasminogen activator inhibitor 1 (PAI1), both leading to an increase in vascular resistance resulting in hypertension seen in patients with chronic kidney disease (CKD)." (PMID 35812547, 2022). "The role of endothelin-1 (ET-1) in the pathogenesis of hypertension (HTN) is not clearly established." (PMID 35366246, 2021). "A beneficial effect of triterpenes on endothelial function and blood pressure has been described in animal models of hypertension, but further studies are required to explore the mechanisms involved in the effect of specific components of VOO on endothelin-1 regulation." (PMID 29772657, 2018). "Endothelin-1, which is a potent vasoconstrictor, is increased with VEGF inhibition, and endothelin antagonism appears to limit the development of hypertension, although the mechanism by which VEGF inhibitors activate endothelin-1 has not been clearly established." (PMID 29399333, 2018). "Additionally, the EA-induced suppression on the pathological progression from hypertension to cardiovascular remodeling in SHR was also likely mediated via the downregulation of Ang 2, ATIR, endothelin type A receptor (ETAR), and endothelin-1 (ET-1)." (PMID 28293268, 2017). "Circulating endothelin-1 levels were similar in participants with or without hypertension (women: 2.4 pg/ml, SE: 0.04 vs 2.5 pg/ml, SE: 0.10, p = 0.801; men: 2.3 pg/mL, SE: 0.04 vs 2.3 pg/ml, SE: 0.09, p = 0.434)." (PMID 26573599, 2015). "Further, in women the association between endothelin-1 levels and CHD remained significant after adjustment for age in combination with WHR, BMI, LDL-cholesterol, HDL-cholesterol, hypertension, CRP, triglycerides or medications (data not shown)." (PMID 26573599, 2015). "The cardiac eNOS-derived NO and the endothelin-1 (ET-1) systems are closely related, and both play a crucial regulatory role in the modulation of cardiac physiology: An imbalance in these two systems can be deleterious in eliciting several CVD such as hypertension and stroke." (PMID 35072089, 2022). "Summing up the results of existing studies, we can learn that several proteins are involved in regulating the progression of high blood pressure, such as endothelin-1, Rac1, and G protein-coupled estrogen receptor, but hypertension-related genes have not been identified systemically." (PMID 33621262, 2021).
Hypertension (continued). "Another study reported that patients with sunitinib-related hypertension showed a twofold increase in plasma endothelin-1 (p-ET-1); intriguingly, this hypertensive effect did not occur when it was associated with the endothelin-1 (ET-1) receptor inhibitor in rats." (PMID 30597890, 2018). "Although, a specific pathophysiological mechanism linking hypertension with psoriasis has not been determined, but increased blood pressure in psoriasis patients can be related to an increased level of angiotensin-converting enzyme, endothelin-1 (ET-1) and rennin." (PMID 36261848, 2022). "Additionally, in diabetic rats, sitagliptin prevented the expression of endothelin-1 (ET-1) in the aortic endothelium via inhibiting the NF-κB/inhibitor of the NF-κB system by activation of the AMPK pathway, which produces a vascular protection function against hypertension." (PMID 34489872, 2021). "In addition, mediators such as endothelin-1 (ET-1), angiotensin II (ANG-II), and cyclooxygenase-derived (COX) eicosanoids also compromise endothelium-dependent vasodilation, resulting in increased vasoconstrictor tone, which eventually drives to CVDs, such as hypertension." (PMID 32454933, 2020). "Furthermore, to clarify which hypertension-related stress activates leptin and leptin receptor expression, we measured leptin and leptin receptor mRNA expression in isolated ventricular myocytes stimulated with angiotensin-II (ANGII), endothelin-1 (ET-1), or mechanical stretch." (PMID 23270329, 2012).